EGFR (epidermal growth factor receptor)
Diseases named in the same sentence as EGFR in open-access papers (continued):
Sharing a sentence is not in itself a finding about the gene and the disease.
breast carcinoma (continued). "It was shown that ZHER2 molecules neither induce toxic effects on breast cancer cells or normal lung fibroblast nor trigger activation of EGFR signaling as the phosphorylation levels of MAPK and AKT were not upregulated after exposure to Affibody." (PMID 22911732, 2012). "EGFR (p = 0.005) and CCND1 (p = 0.041) copy number gain were independent predictors of gender in logistic regression, and these genes were more often gained in male breast cancer." (PMID 22527098, 2012). "Beside CXCR4 expression, a phenotypic characterization of the cells from the primary cultures was performed, by analyzing the expression of common mammary lineage markers (CK14, CK18, EMA, ER-α), or proteins (EGFR and HER-2/neu) overexpressed in mammary carcinoma conferring malignant behaviour." (PMID 22417013, 2012). "The overall goal of this study was to assess the level of heterogeneity of protein expression in breast cancer specimens by analyzing 35 target proteins including 15 phosphorylated proteins representing the HER2, EGFR, and uPA/PAI-1 signaling pathways relevant to breast cancer." (PMID 22792263, 2012). "Moreover, lapatinib, an oral dual selective inhibitor of the tyrosine kinase domain of EGFR and HER2, increased the sensitivity of breast cancer cells to 4-hydroxy-tamoxifen, restoring endocrine sensitivity." (PMID 23344024, 2012). "Recent whole-genome expression profiling of breast cancers has revealed that the hypoxic response (predominantly through HIF-1α), the EGFR and signal transducer and activator of transcription 3 (STAT3) pathways are positively correlated together in TNBCs as compared to luminal cancers." (PMID 22225988, 2012). "Additionally, there has been extensive data, particularly in breast cancer research, demonstrating crosstalk between estrogen signaling and ErbB2/HER2/neu, a membrane tyrosine kinase epidermal growth factor receptor, regulating MAPK and AKT signaling." (PMID 23300682, 2012). "This is the first report implying the reciprocal regulation of Her-2 and AnxA2 and the role of AnxA2 in Her-2 negative breast cancer and EGFR signaling." (PMID 22957061, 2012). "The ability of curcumin to downregulate EGFR and HER-2 oncoproteins and inhibit the phosphorylation of Akt and MAPK and NF-κB activation suggests that curcumin has potential in the treatment of HER-2-overexpressed and/or herceptin-resistant breast cancer." (PMID 21876713, 2012). "We also analyzed the mRNA expression of HER-1 (also known as epidermal growth factor receptor EGFR), HER-3 and HER-4, known to share functional properties with HER-2, but much less studied in breast cancer." (PMID 22703232, 2012). "We show that somatic mutations frequently observed in breast cancer lead to β-catenin activation: this observation strengthens emerging data outlining the relevance of the β-catenin activation in breast cancer and the crosstalk between EGFR and WNT signals in breast cancer development." (PMID 22662165, 2012). "Although lapatinib blocks EGFR kinase activity, the contribution of this function to anticancer activity in HER2-positive breast cancer cells appears to be minimal, as loss of HER2 expression reduced lapatinib efficacy, while loss of EGFR expression did not." (PMID 23227361, 2012). "High expression of EGFR and HER2 in ER(−) breast cancers were found, suggesting that activation of growth factor signaling and consequently, the activation of MAPK might contribute to transcriptional repression of ER gene, resulting in endocrine resistance." (PMID 23344024, 2012). "Consistently in this study, we noticed that when MDA-MB-231 and MCF-7 breast cancer cells were pretreated with AG1478, EGF-induced EGFR phosphorylation was blocked, and resulted in the inhibition of EGF-stimulated ERK1/2 phosphorylation and cell proliferation (data not shown)." (PMID 22476347, 2012).
breast carcinoma (continued). "Furthermore, SHIP2 is a positive regulator of the epidermal growth factor receptor/Akt pathway, C-X-C chemokine receptor type 4 expression, and cell migration in MDA-MB-231 breast cancer cells." (PMID 22121480, 2012). "In male breast cancer CCND1 and EGFR were more often gained than in the female breast cancer group." (PMID 22527098, 2012). "In a breast cancer mouse model, mucin 1 (MUC1 for human and Muc1 for nonhuman species) facilitated TGFα-induced EGFR activation and breast cancer development." (PMID 22457794, 2012). "It has some overlap with basal like breast cancer, but the overlap is not complete, because basal like subtype overexpresses myoepithelial cytokeratins (CKs) such as CK 5/6, CK 17 and EGFR." (PMID 23046633, 2012). "Basal-like breast carcinomas have variable expressions of basal cytokeratins (CKs) (CK5/6, CK14, CK17), vimentin, myoepithelial markers (smooth muscle actin, p-63), CD117, P-cadherin and/or human EGFR (HER1/EGFR)." (PMID 23082819, 2012). "We showed that 80% of all breast cancers express at least one of a panel of markers (CD44v6, GLUT1, EGFR, HER2, and IGF1-R) that therefore may be suitable for molecular imaging strategies." (PMID 22695343, 2012). "It is established that EGFR and Src expression is upregulated in Her-2 negative and Herceptin-resistant breast cancers." (PMID 22957061, 2012). "For example, the androgen (AR) and estrogen (both ESR1 and ESR2) nuclear hormone receptors are known to be relevant in prostate and breast cancers, and the alpha-type platelet-derived (PDGFRA) and epidermal (EGFR) growth factor receptors are recognised angiogenesis factors." (PMID 22558171, 2012). "We clearly show that the stability of EGFR protein is reduced in MUC1 knockdown cells, suggesting that MUC1 potentiates BPDE-induced EGFR activation through stabilization of the latter, similarly as in ligand-induced EGFR activation in breast cancer cells." (PMID 22457794, 2012). "This was observed in both breast cancer and GBM datasets and leaves open the possibility that selection of well-known drivers such as ERBB2 and EGFR may be synergistically acting on altered metabolic processes abrogated by co-altered, nearby metabolism genes." (PMID 23383675, 2012). "In breast cancer models, however, EGFR overexpression alone usually does not constitute efficient transformation and tumorigenesis while co-expression with the non-receptor kinase c-Src dramatically increases tumorigenesis 7–9." (PMID 22927910, 2012). "Although IBC do not exhibit a specific expression profile, they tend to aggregate poor prognosis breast cancer clusters, being commonly of basal-like subtype, showing Her-2 amplification, EGFR overexpression and lacking estrogen and progesterone receptors." (PMID 22666420, 2012). "Similarly, synergistic effects of lapatinib in combination with fulvestrant have been reported in breast cancer cell lines expressing differential amounts of ER, HER2 and EGFR." (PMID 23344024, 2012). "In breast cancers and head and neck SCC (HNSCC), a strong correlation between Stat3 and EGFR expression has been observed, and it has been suggested that the JAK/STAT pathway is one of the important downstream routes for EGFR signaling." (PMID 21197106, 2011). "This property of AST1306 is consistent with that of lapatinib that its activity is not dependent on EGFR expression level in ErbB2-overexpressing breast cancer cells." (PMID 21789172, 2011). "Additional reports have characterized a relationship between IGF-1R and EGFR signaling in aggressive, drug-resistant breast cancer cells and have speculated that IGF-1R signaling plays a role in the development of gefitinib resistant EGFR tumors." (PMID 21854628, 2011). "In addition, growth factor receptors (GFR), including insulin-like growth factor receptor (IGFR) and epidermal growth factor receptor (EGFR), are the other E2-membrane signaling pathways within breast cancer cells." (PMID 21617769, 2011).
breast carcinoma (continued). "Researchers in recent studies have pointed out that numerous signaling pathways, including the epidermal growth factor receptor, HER2, IGFR and BRCA1/2 pathways, could contribute to the malignancy of ER- breast cancer." (PMID 22113133, 2011). "To explore this hypothesis, we investigated the frequency of maspin expression and its correlation with established basal (CK5/6, EGFR, CK14) and myoepithelial (p63, CD10) markers in TN breast cancer." (PMID 21496280, 2011). "In recent years, EGFR tyrosine kinase inhibitors have received FDA (Food and Drug Administration) approval and are currently being tested in patients with lung, gastric, and breast cancer." (PMID 21730982, 2011). "For example, overexpression of cErbB2 or of EGFR in breast cancer marks worse course of disease not only in ERα-negative, but also in ERα-positive tumors and is a marker for tamoxifen resistance as well." (PMID 22295213, 2011). "Noticeably, both the GBM and breast cancer cell lines we analyzed contained a basal level of mitochondrial EGFR without stimulation." (PMID 21388543, 2011). "Secondly, a growing body of evidence suggests that heparanase, a downstream target of EGFR/HER2, might be involved in BM from breast cancer." (PMID 22567347, 2011). "Our data show that the EGFR inhibitor erlotinib was effective in the prevention of EGFR+/ER- breast cancers, but not EGFR-/ER+ breast cancers, in BRCA1-mutant mice." (PMID 21396117, 2011). "Aplidin induces apoptosis in MDA-MB-231 breast cancer cells, resulting in sustained activation of the epidermal growth factor receptor (EGFR), the non-receptor protein-tyrosine kinase Src, and the serine/threonine kinases JNK and p38 MAPK." (PMID 22072999, 2011). "Kp-10 did not enhance invasion of breast cancer cells when EGFR was inhibited through the use of tyrosine kinase inhibitor AG1478, suggesting EGFR involvement in Kp-10-stimulated invasion." (PMID 21738726, 2011). "In a recent study that analyzed the spectrum of molecular subtypes of breast cancer in a Saudi population, we noticed (but have not reported) a remarkably low incidence of EGFR protein expression in our patients." (PMID 21702909, 2011). "Hypothetically, clinical testing of dual inhibitors of EGFR and HER2, such as lapatinib, neratinib, and BIBW 2992 (afatinib), might thus be of particular interest in the relatively small subset of breast cancer patients whose disease first recurs in the lungs." (PMID 21914172, 2011). "Both selective EGFR inhibitor AG 1478 and selective MEK inhibitor PD 98059 were observed to be able to block this signaling pathway and prevent versican G3 induced effects on mammary cancer cell proliferation." (PMID 22096483, 2011). "For example, ER mRNA and protein can be downregulated in MCF-7 cells by stably overexpressing EGFR or constitutively activating erbB-2, Raf, or MEK; and in a number of ER- breast cancers, ER expression can be restored by inhibiting GFR through targeting of MAPK/ERK." (PMID 20569503, 2010). "Basal-like breast cancer has similarities with normal breast basal epithelial cells and is commonly identified by a lack of ER and HER2 receptor expression and by the expression of either cytokeratin 5/6 or epidermal growth factor receptor (EGFR)." (PMID 20520798, 2010). "As expected, lapatinib inhibited EGFR and HER2 phosphorylation in SKBR3 breast cancer cells." (PMID 21080941, 2010). "Breast cancers show a lack of response to epidermal growth factor receptor (EGFR) tyrosine kinase inhibitors (TKIs), despite 30% of tumors expressing EGFR." (PMID 20624308, 2010). "This is the first report of EGFR and Met physically interacting and EGFR regulating Met activation in the absence of HGF in breast cancer." (PMID 20624308, 2010). "We have shown that in an EGFR TKI resistant breast cancer cell line, Met was constitutively activated independent of ligand." (PMID 20624308, 2010).
breast carcinoma (continued). "Coactivator overexpression in human breast cancer cell lines increased proliferation with resistance to PPAR and RXR ligands and remodeled chromatin of the proximal epidermal growth factor receptor promoter, which is a principal growth signaling pathway in mammary epithelial cells." (PMID 21080969, 2010). "EGFR, c-Kit (also known as CD117) and vascular endothelial growth factor (VEGF) are candidate biomarkers of basal-like breast cancer with targeted therapies in development." (PMID 24281106, 2010). "Both selective EGFR inhibitor AG 1478 and selective MEK inhibitor PD 98059 could block this signaling pathway and prevent versican G3 induced effects on mammary cancer cell proliferation." (PMID 21079779, 2010). "It has been suggested that thrombin indirectly induces cellular rearrangements by activating PAR1 and transactivating the epidermal growth factor receptor (EGFR and/or HER2) poor prognosis factors for breast cancer patients, which exerts its effects exclusively through intracellular signals." (PMID 19538737, 2009). "In addition, overexpression of caveolin-1 in the MCF-7 breast cancer cell line has been shown to modulate EGFR activation levels and EGF-induced EGFR signaling." (PMID 19816600, 2009). "In the main part of this study, the expression of the panel of 5 RT-PCR markers (TACSTD1, EPHB4, ELF3, EGFR, and MGB1) was determined after immunobead enrichment of circulating epithelial cells in blood samples obtained from 56 early stage breast cancer patients." (PMID 19500345, 2009). "If α6β4 functions, in part, to recognize this vascular address, EGFR may help to mediate the translocation of tumor cells into the adjacent tissue, as EGF has been shown to be a potent chemotactic factor for breast carcinoma cells." (PMID 19470173, 2009). "Immunomagnetic enrichment of circulating tumour cells followed by RT-PCR (immunobead RT-PCR) with a panel of five epithelial specific markers (ELF3, EPHB4, EGFR, MGB1 and TACSTD1) was used to screen for circulating tumour cells in the peripheral blood of 56 breast cancer patients." (PMID 19500345, 2009). "As some of these features are basal-cell markers (such as EGFR, CK5, P-Cadherin), CUL4A may play an important role in the biology of basal-like breast cancers." (PMID 19995430, 2009). "In addition, in human HNSCC and breast cancer cell lines EGCG inhibits the constitutive activation of the transcription factor Stat3, which also lies downstream of EGFR." (PMID 19325845, 2008). "Based on expressions of EGFR, ER and c-erbB-2, only two carcinomas were classified as breast carcinomas of basal-like phenotype (EGFR-positive, ER-negative and c-erbB-2 negative)." (PMID 18522728, 2008). "Moreover, interactions between EGFR and HER2 with respect to the prognosis of breast cancer patients have been reported." (PMID 18985033, 2008). "To investigate expression levels of EGFR, HER2, PI3K, and Akt in circulating tumor cells, we used peripheral blood mononuclear cells from 32 cytokeratin-19 mRNA-positive patients with early (n = 16) and metastatic (n = 16) breast cancer." (PMID 18822183, 2008). "The combined therapy of Herceptin and Iressa is additive in suppression of EGFR and HER2 activation as well as exerting its anti-proliferative effect, consistent with the report that combination of targeted therapies against both EGFR and HER2 is more effective that single agents in breast cancer." (PMID 18682844, 2008). "Interrupting the ERBB2-ERBB3 heterodimer using lapatinib (GW572016, GlaxoSmithKline), a potent small-molecule inhibitor of EGFR and ERBB2 tyrosine kinases, leads to proteasomal degradation of BIRC5 and induces apoptosis both in breast cancer cell lines overexpressing ERBB2 and in primary tumors." (PMID 19007432, 2008). "As both YB-1 and EGFR are expressed in BLBC, we questioned whether there was a relationship between these two genes in this particular subtype of breast cancer." (PMID 17875215, 2007).
breast carcinoma (continued). "EGFR and HER2 immunoassays were conducted in blood from 57 patients in whom paired serum samples were available (from the times of primary and metastatic diagnoses), from 96 primary breast cancer patients and from 49 normal individuals." (PMID 17976236, 2007). "The erbB (human epidermal growth factor receptor [HER]/neu 1 to 4) receptors are a family of four known receptors localized on the cell membrane of most tumours, including breast cancer." (PMID 17976236, 2007). "Inhibition of EGFR and Src kinases did not have an effect on pStat3, suggesting that these kinases are not direct mediators of Stat3 phosphorylation in these breast cancer-derived cell lines." (PMID 17531096, 2007). "Thus, we demonstrate a direct relationship between the degree of efficacy of anti-EGFR regimens and the levels of HER2 expression in breast cancer cell lines." (PMID 16622439, 2006). "In a cohort of 130 breast carcinomas, an inverse correlation was found between nuclear EGFR, but not the non-nuclear counterpart, and overall patient survival." (PMID 16434982, 2006). "This would suggest the possibility that HER2 overexpression alone and/or the combination of EGFR and HER3 expression levels might be useful clinical markers for response to EGFR and combined EGFR–HER2 targeted therapy in patients with breast cancer." (PMID 16622439, 2006). "In this respect, it has been shown that the EGFR-dependent autocrine pathway plays a key role both in intrinsic or de novo resistance to tamoxifen in ER positive, HER2 overexpressing MCF-7 breast cancer cells and in the acquired resistance to tamoxifen in tamoxifen-treated MCF-7 cells." (PMID 16685276, 2006). "In fact, the growth-inhibitory effect of gefitinib has been reported to be independent of the levels of expression of EGFR in human breast cancer cells and other cancer cell lines." (PMID 15987464, 2005). "Three out of nine carcinomas with squamous metaplasia and four out of 10 spindle cell carcinomas had EGFR amplification, whereas no matrix producing breast carcinomas showed any amplification." (PMID 16280056, 2005). "EGFR/ERBB1 is overexpressed in 35% to 60% of breast cancers, which correlates with a negative steroid receptor status, increased ERBB2 and VEGF (Vascular endothelial growth factor) expression." (PMID 16168117, 2005). "To further confirm our investigation on increased phosphorylation in breast cancers, we have applied IHC staining on breast tumours fixed on TMA slides to examine the phosphorylation status of PDK-1, AKT, mTOR, p70S6K, S6, Stat3, and EGFR." (PMID 16288304, 2005). "Furthermore, high expression of FAK in breast cancer is related to activation of AKT and to the overexpression of receptor molecules such as ErbB2/Her2 and EGFR." (PMID 16288304, 2005). "Most importantly, in recent years EGFR tyrosine kinase inhibitors and humanized monoclonal antibodies against HER2 have received US Food and Drug Administration approval and are currently being tested in patients with lung and breast cancer." (PMID 16280056, 2005). "In one study, the sensitivity of a panel of human breast cancer and other epithelial tumour cell lines to gefitinib was found not to be dependent on overexpression of EGFR, and was also suggested to be related to erbB2 expression." (PMID 15083203, 2004). "Furthermore, the genes mammaglobin, epidermal growth factor receptor (EGFR) and SBEM were tested, described in the literature as breast cancer marker genes." (PMID 15083181, 2004). "This study determined whether there is a correlation between EGFR/HER2 status and MAPK (ERK1/2) phosphorylation in breast cancer cells, and how this affects the response to an inhibitor of the receptors." (PMID 15280923, 2004). "The levels of mRNA for transforming growth factors (TGF alpha and beta) and the epidermal growth factor receptor (EGFR) were determined in 69 human breast carcinomas and 20 biopsies of non-neoplastic breast tissue by dot blot hybridisation analysis." (PMID 2331446, 1990).